ERCC1 (ERCC excision repair 1, endonuclease non-catalytic subunit)
Diseases named in the same sentence as ERCC1 in open-access papers (continued):
Sharing a sentence is not in itself a finding about the gene and the disease.
breast carcinoma (continued). "In further subgroup analysis by ethnicity, the ERCC1 rs11615 polymorphism was associated with an increased risk of breast cancer in Asian populations." (PMID 29752341, 2018). "It was reported that higher expression of ERCC1 is associated with favorable prognostic factors for early stage breast cancer patients, but with poor outcome for those metastatic TNBC patients treated with platinum-based chemotherapy." (PMID 30096175, 2018). "Our pooled study demonstrated a clear increase in breast cancer risk associated with the ERCC1 rs11615 polymorphism under all genetic models (all P<0.05)." (PMID 29752341, 2018). "Previously, ERCC1 variants have been found to be associated with carcinogenesis in various types of cancer, such as lung, colorectal, gastric and ovarian, as well as breast cancer." (PMID 30096175, 2018). "Much attention has been drawn to heritable polymorphisms in DNA repair genes in relation to breast cancer risk; amongst such genes, ERCC1 is highly polymorphic." (PMID 29752341, 2018). "In conclusion, our meta-analysis does demonstrate that the ERCC1 rs11615 polymorphism significantly increases the risk of breast cancer." (PMID 29752341, 2018). "In the end, seven case–control studies about the ERCC1 rs11615 polymorphism and breast cancer risk were included in our study, encompassing 2354 cases and 2193 controls." (PMID 29752341, 2018). "Several case–control studies focussed on the ERCC1 rs11615 gene polymorphism and breast cancer risk have produced mutually contradictory results." (PMID 29752341, 2018). "We have already shown that breast cancer patients with CTCs detected after neoadjuvant chemotherapy were associated with tumor stem cell characteristics and ERCC1-expression." (PMID 28388557, 2017). "For ERCC1 rs11615, the pooled results indicated that TT and TT/CT genotype were associated with increased breast cancer risk." (PMID 27768589, 2016). "Numerous studies have reported that high/positive ERCC1 expression is associated with the prognosis of other types of cancer, including non-small cell lung, bladder, colorectal and breast cancer." (PMID 25780441, 2015). "The 8092A and 19007C genotypes in ERCC1 were significantly associated with overall survival in T4 breast cancer patients treated with chemotherapy containing platinum (p-values = 0.036 and 0.004, respectively)." (PMID 25253066, 2014). "In the present study, we evaluated the prognostic role of the two most common ERCC1 polymorphisms in patients with T4 breast cancer receiving platinum-based chemotherapy." (PMID 25253066, 2014). "Accordingly, it was recently reported that three markers, RAI, ASE-1 and ERCC1, in the same chromosomal region 19q13.2-3 define a high-risk haplotype that poses women under 55 years to a significantly increased breast cancer risk." (PMID 16280050, 2005). "In addition, the combined diagnosis of XRCC4, PARP1, and excision repair cross-complementation group 1 (ERCC1) has demonstrated considerable predictive capability in assessing the risk of breast cancer metastasis." (PMID 37679817, 2023). "However, there is a discrepancy in our understanding of the association between ERCC1 and breast cancer." (PMID 36338712, 2022). "In addition, the combined diagnosis of PARP1, XRCC4 and ERCC1 has great predictive value for the risk of breast cancer metastasis." (PMID 33184404, 2020). "In protein expression, PARP1 (OR 1.147, 95% CI 1.067 ~ 1.233, P < 0.05), XRCC4 (OR 1.088, 95% CI 1.015 ~ 1.166, P < 0.05), XRCC1 (OR 1.114, 95% CI 1.021 ~ 1.215, P < 0.05), ERCC1 (OR 1.068, 95% CI 1.000 ~ 1.141, P < 0.10) were risk factors for postoperative metastasis of breast cancer." (PMID 33184404, 2020). "In addition, Uygur patients with breast cancer with 2‐3 combined risk genotypes of ERCC1 had a higher risk than patients with 0‐1 risk genotypes (OR = 2.91; 95% CI = 1.54‐5.71, p = 0.001)." (PMID 33067872, 2020).
breast carcinoma (continued). "In addition, we found that Uygur patients with breast cancer with 2‐3 combined risk genotypes of ERCC1 had a higher risk than that of individuals with 0‐1 risk genotypes (OR = 2.91; 95% CI = 1.54‐5.71, p = 0.001)." (PMID 33067872, 2020). "ERCC1/XPF gene polymorphisms predispose Uygur individuals to breast cancer." (PMID 33067872, 2020). "Therefore, it is necessary to explore the contribution of ERCC1/XPF gene polymorphisms to breast cancer risk in specific populations, including the Xinjiang Uygur and Han groups." (PMID 33067872, 2020). "The increased risk of breast cancer under the allele model, heterozygous model and dominant model was still nominally significant (P=0.02, P=0.007, and P=0.01, respectively), which further confirmed the significant role played by ERCC1 rs11615 in breast cancer susceptibility." (PMID 29752341, 2018). "In addition, a pooled result showed that within Caucasian population, individuals with the ERCC1 rs3212986 gene polymorphism suffer a higher risk of breast cancer." (PMID 29752341, 2018). "Thus, we performed this meta-analysis based on the available case–control studies to expound the effect of the ERCC1 rs11615 polymorphism on breast cancer risk." (PMID 29752341, 2018). "From the 5-fluorouracil-, doxorubicin- and cyclophosphamide-induced DNA repair viewpoint, the genotypes of either ERCC1 rs11615 or rs3212986 may cause the differential responses to these drugs in TNBC or other subtypes of breast cancer patients." (PMID 30096175, 2018). "To date, the risk of breast cancer conferred by the ERCC1 rs11615 polymorphism in relation to menopausal status has not been widely and thoroughly investigated and may be a promising area for breast cancer research." (PMID 29752341, 2018). "Well-designed case–control studies with larger sample sizes and examining populations from across the world are essential for the exploration of the association between breast cancer risk and ERCC1 gene polymorphisms, other DNA repair gene polymorphisms, and even the relevant haplotypes." (PMID 29752341, 2018). "Notably, the association of ERCC1 polymorphisms with breast cancer has been revealed in different countries, including Korea, United States, Iran, China and Thailand." (PMID 30096175, 2018). "In the allelic frequency distribution analysis, breast cancer patients carried the T allele of ERCC1 rs11615 a higher rate than the control subjects, further supporting the idea that ERCC1 rs11615 TT genotype is positively associated with breast cancer susceptibility." (PMID 30096175, 2018). "In conclusion, the present case-control study, with a very large sample, indicates that the T allele of ERCC1 rs11615 may potentially serve as a powerful marker for the prediction of breast cancer, especially for TNBC." (PMID 30096175, 2018). "While ERCC1 rs11615 have a high risk of ER+ and PR+ breast cancer and PR." (PMID 27768589, 2016). "In addition, ERCC1 rs11615 carriers have a high risk of breast cancer with grade 3, while XPC rs2228000 and ERCC2/XPD rs50872 are linked to a high risk for breast cancer with grades 1 and 2, respectively." (PMID 27768589, 2016). "Therefore, ERCC1 rs11615 T allele carriers (CT/TT) exhibited reduced ERCC1 expression and higher breast cancer risk, which was consistent with our results." (PMID 27768589, 2016). "This case-control study revealed the susceptibility of carriers of ERCC1 variant rs11615 to increased risk of breast cancer, consistent with previous observations that ERCC1 rs11615 was associated with reduced mRNA and protein expression levels, and consequently impaired DNA repair capacity." (PMID 27768589, 2016). "To this aim, we here assessed that the ERCC1 gene polymorphisms may play an analogous clinical role as predictive and prognostic factor among patients with T4 breast cancer receiving platinum-based therapy." (PMID 25253066, 2014).
breast carcinoma (continued). "However, to our knowledge, this is the first study clearly demonstrating that polymorphisms in ERCC1 gene are significantly associated with overall survival in patients with T4 breast cancer receiving platinum-based treatment." (PMID 25253066, 2014). "In this study, two single nucleotide polymorphisms, C8092A and T19007C, in ERCC1 gene were retrospectively evaluated for their association with the clinical behavior in a group of T4 breast carcinoma patients of Sardinian origin, receiving platinum-based chemotherapy." (PMID 25253066, 2014). "ERCC1 polymorphism may be associated with increased breast cancer risk." (PMID 31405143, 2019). "In addition, the T allele of ERCC1 rs11615 was common in patients with breast cancer." (PMID 30096175, 2018). "A study by Li, Liao, and Ma proved the poor prognostic value of ERCC1 in patients with HER2neu-expressing breast cancer, as evidenced by lower disease-specific survival and overall survival in ERCC1-positive patients." (PMID 40008380, 2025). "High expression of ERCC1 suggests a poor prognosis for patients with HER2 over-expressing breast cancer." (PMID 36338712, 2022). "Further, the correlation between infiltrating immune cells and ERCC1 expression in patients with HER2 over-expressing breast cancer was evaluated." (PMID 36338712, 2022). "Therefore, the ERCC1 methylation could be associated with the occurrence of breast cancer." (PMID 36338712, 2022). "High-level expression of ERCC1 usually indicate the higher resistance of chemotherapy in breast cancer." (PMID 36338712, 2022). "Further, the correlation between ERCC1 expression, immune cell infiltration clinicopathological features, and the prognosis of patients with breast cancer was analyzed." (PMID 36338712, 2022). "Various studies have explored the effect of ERCC1 expression on the prognosis of a patient with different molecular subtypes of breast cancer." (PMID 36338712, 2022). "Another study showed that the expression of ERCC1 in ER-positive patients with breast cancer after neoadjuvant chemotherapy is significantly lower than that of ER-negative patients." (PMID 36338712, 2022). "The IHC scores of PARP1, XRCC4 and ERCC1 were higher than that of 6, 6 and 3 breast cancer metastasis, respectively." (PMID 33184404, 2020). "In breast cancer, ERCC1 C8092A (rs3212986) and C118T (rs11615) genotypes predicted a more favorable prognosis in locally advanced breast cancer treated with platinum-based chemotherapy." (PMID 33266377, 2020). "Stratification analysis for the association between ERCC1/XPF gene genotypes and Han breast cancer susceptibility." (PMID 33067872, 2020). "PARP1, XRCC4, ERCC1 is also found to be an independent factor for postoperative metastasis of breast cancer." (PMID 33184404, 2020). "In order to further understand the role of PARP1, XRCC4 and ERCC1 in predicting the prognosis, metastasis of breast cancer, we also studied the best cut-off value of PARP1, XRCC4 and ERCC1." (PMID 33184404, 2020). "This is the first study of the association between ERCC1/XPF polymorphisms and susceptibility to breast cancer in Uygur and Han populations in Xinjiang." (PMID 33067872, 2020). "So we combined protein expression (IHC score) of PARP1, XRCC4 and ERCC1 to detect the prognosis of breast cancer." (PMID 33184404, 2020).
breast carcinoma (continued). "Distribution of ERCC1/XPF gene polymorphisms in Han and Uygur women with breast cancer was different." (PMID 33067872, 2020). "We performed the first case–control study of the role of ERCC1/XPF polymorphisms in Han and Uygur patients with breast cancer." (PMID 33067872, 2020). "Given the critical role of ERCC1 in genomic integrity, in the current study, we evaluated the role of ERCC1 as a biomarker in breast cancers." (PMID 31405143, 2019). "We provide the first comprehensive clinical evidence that ERCC1 is a key predictor of chemotherapy response in patients with breast cancer who receive adjuvant or neoadjuvant chemotherapy." (PMID 31405143, 2019). "Taken together, the data presented here provides comprehensive clinical evidence that ERCC1 is a predictor of anthracycline resistance and taxane sensitivity in breast cancers." (PMID 31405143, 2019). "Taken together, the data would support further development of ERCC1 as a biomarker of response to chemotherapy in breast cancer." (PMID 31405143, 2019). "More importantly, the frequency of the ERCC1 rs11615 TT genotype was even higher among TNBC patients than among other subtypes of breast cancer patients (P = 0.0001, odds ratio = 1.73, 95% confidence interval = 1.15–2.63)." (PMID 30096175, 2018). "Distribution of Excision Repair Cross-complementing Group 1 (ERCC1) genotypes among the breast cancer and the control woman." (PMID 30096175, 2018). "Distribution of Excision Repair Cross-complementing Group 1 (ERCC1) allelic frequencies among the breast cancer patients and control women." (PMID 30096175, 2018). "This assumption is strongly supported by our previous studies on breast cancer patients, in which we already showed that preferentially semi-mesenchymal and potentially platinum-resistant (ERCC1-expressing) CTCs remain after neoadjuvant chemotherapy." (PMID 28415744, 2017). "We found that carriers of the T allele of ERCC1 rs11615, XPC rs2228000 and rs50872, particularly in postmenopausal females, have an increased risk of breast cancer." (PMID 27768589, 2016). "In conclusion, our study deduced that ERCC1 rs11615 (CT or CT/TT), XPC rs2228000 (TT or CT/TT) and rs50872 (CT or CT/TT) were risk factors associated with increased breast cancer incidence, especially in postmenopausal women." (PMID 27768589, 2016). "Additionally, in our study the increased risk of breast cancer linked to ERCC1 rs11615 more prominent in postmenopausal females and patients with positive expression of PR and ER, indicating the risk conveyed by this polymorphism to breast cancer in menopausal females." (PMID 27768589, 2016). "The result showed that ERCC1 rs11615, XPC rs2228000, and ERCC2/XPD rs50872 carriers have a higher breast cancer risk in the whole study population." (PMID 27768589, 2016). "While in the postmenopausal sub-cohort, ERCC1 rs11615 and ERCC2/XPD rs50872 were associated with increased breast cancer risk." (PMID 27768589, 2016). "This case-control association study revealed that ERCC1 rs11615 (T allele), XPC rs2228000 (T allele) and ERCC2/XPD rs50872 (T allele) were associated with increased breast cancer risk." (PMID 27768589, 2016). "In conclusion, BRCA1 (Pro871Leu), ERCC1 (Asn118Asn), CYP1B1 (Leu432Val), and SLCO1B3 (rs11045585) are associated with response to NCT in our cohort of breast cancer patients." (PMID 26180747, 2015). "This is the first study analyzing the SNPs in ERCC1 and ERCC2 genes and the susceptibility to cancer in Mexican-mestizo patients with osteosarcoma, and colorectal and breast cancer." (PMID 25789018, 2015). "The aim of the present study was to test for an association between the Asn118Asn (ERCC1), Lys751Gln and Asp312Asn (ERCC2) variants, and osteosarcoma and colorectal and breast cancer in Mexican patients." (PMID 25789018, 2015).
breast carcinoma (continued). "The aim of the present study was to investigate whether the ERCC1 19007C > T and 8092C > A polymorphisms may influence the clinical outcome in response to treatment with platinum within a well-characterized cohort of patients with T4 breast carcinoma and long follow-up evaluation." (PMID 25253066, 2014). "Breast cancer proliferative genes, such as aurora kinase, ERCC1, IGFBP3 were inhibited and growth inhibitory genes, such as NQO1, PTPRJ were activated by GTx-027." (PMID 25072326, 2014). "Some SNPs in DNA repair related genes, such as APE1, XRCC1, ERCC1 and XPF were found to be associated with breast cancer susceptibility in Chinese Han population, so did some SNPs in cell-cycle genes such as CCNE1 and CDK2." (PMID 24386390, 2013). "This in vitro study found that EMD can significantly reverse the multi-drug resistance and reduce ERCC1 expression in breast cancer cells." (PMID 23046742, 2012). "In this study, we investigated the effects of emodin on reversing the multi-drug resistance, examined the ERCC1 protein expression in breast cancer cell line, and explored the relationship between reversal of multi-drug resistance and ERCC1 protein expression." (PMID 23046742, 2012). "Nevertheless, we believe further studies on ERCC1 expression in breast cancer and emodin in facilitating the reversal of drug resistance are warranted." (PMID 23046742, 2012). "Drug sensitivity and ERCC1 expression were studied, so as to explore the role of ERCC1 in breast cancer multi-drug resistance and the effect of EMD on reversing such resistance." (PMID 23046742, 2012). "Using the 8F1 CC1-mono protocol, lung and breast carcinomas had lower ERCC1 expression in comparison to the other entities (p-value < 0.05)." (PMID 21961533, 2011). "Our current study focus on two promising biomarkers, ERCC1 (excision repair cross-complementing group 1) and BRCA1 (breast cancer susceptibility gene 1)." (PMID 18402708, 2008). "A retrospective cohort study of 105 Taiwanese breast cancer patients treated with palbociclib, a targeted CDK4/6 inhibitor, examined the prevalence of neutropenia associated with four SNPs: ABCB1_rs1045642, ABCB1_rs1128503, ERCC1_rs3212986, and ERCC1_rs11615." (PMID 40227705, 2025). "ERCC1 has both prognostic and predictive values in breast cancer; however, previous studies did not establish an association between ERCC1 expression and tumor type or grade." (PMID 40008380, 2025). "ERCC1 expression also affects the chemosensitivity of the breast cancer cells." (PMID 36338712, 2022). "A significant increase in ERCC1 expression in breast cancer tissues compared to normal tissue." (PMID 36338712, 2022). "Further, we aim to explore the immune status of ERCC1 in breast cancer." (PMID 36338712, 2022). "The results revealed that in patients with HER2 over-expressing breast cancer, a positive correlation was observed between ERCC1 expression and TIDE score, suggesting that ERCC1 expression could impact the effects of immunotherapy." (PMID 36338712, 2022). "So we combined PARP1, XRCC4 and ERCC1 to detect the prognosis of breast cancer." (PMID 33184404, 2020). "The role of ERCC1 in breast cancer pathogenesis is emerging." (PMID 31405143, 2019). "ERCC1 based stratification is an attractive strategy for breast cancers." (PMID 31405143, 2019). "Given the key role for ERCC1 in genomic integrity, we hypothesized a role for ERCC1 in breast cancer pathogenesis and response to therapy." (PMID 31405143, 2019). "Our study not only concurs with previous studies showing a link between ERCC1 overexpression and chemoresistance but also provides additional insight suggesting that ERCC1 may also be involved in the emergence of aggressive breast cancer phenotypes." (PMID 31405143, 2019). "Although six prior studies have investigated the correlation between the ERCC1 rs3212986 polymorphism and breast cancer development, no definite conclusions have been reached regarding this causal relationship." (PMID 29752341, 2018).